ENSG00000283663 (novel transcript)
Gene: Protein-coding gene on chromosome 19 (49,055,793 to 49,065,076, reverse strand). Ensembl gene ENSG00000283663.
Genetic constraint (gnomAD): Missense variants: 176 observed, 178.04 expected, observed/expected ratio (o/e) 0.99, 90% interval 0.87 to 1.12. Synonymous variants: 81 observed, 72.64 expected, observed/expected ratio (o/e) 1.12, 90% interval 0.93 to 1.34.